IL6 (interleukin 6)
Diseases named in the same sentence as IL6 in open-access papers (continued):
Sharing a sentence is not in itself a finding about the gene and the disease.
plague (4 papers, 2020 to 2024). Plague is a severe bacterial infection caused by the gram-negative bacterium Yersinia pestis. "The finding that lower BALF IL-6 concentrations correlated with increased survival of Fp T = −3 + Sm 48-treated mice led us to question whether IL-6 drives inflammation associated with lethality in the event of delayed treatment of pneumonic plague." (PMID 34780267, 2022). "We show that the absence of Pla results in increased expression of genes encoding the proinflammatory cytokines IL-6 and IL-17 and the chemokine monocyte chemoattractant protein (MCP-1) early in the lungs during the preinflammatory phase of pneumonic plague." (PMID 37338372, 2023). "We therefore sought to determine how expression of IL-6, MCP-1, and IL-17 impacted the biphasic progression of pneumonic plague." (PMID 37338372, 2023). "Compared to MOD group, we found that ST could effectively decrease the body weight, triglyceride, total cholesterol, IL-6, TNF-α, plague area, numbers of heart lymphatic vessels, and T cells in lymph nodes through p38/JNK/ERK5." (PMID 32765273, 2020). "While the absence of IL-6 and MCP-1 did not significantly alter the progression of disease, we identified IL-17 as a key cytokine that impacts host inflammatory responses during the progression of primary pneumonic plague." (PMID 37338372, 2023).
posterior uveitis (4 papers, 2012 to 2024). Inflammation of the choroid as well as the retina and vitreous body. "We examined an unknown cause of posterior uveitis, collecting vitreous fluid to investigate vitreous IL-6 levels." (PMID 36902507, 2023). "Thus, in the present study, we performed diagnostic vitrectomy for posterior uveitis of an unknown cause then investigated the relevance of vitreous IL-6 levels in conjunction with the manifestations and characteristics of the patients." (PMID 36902507, 2023). "We performed vitrectomy in 37 cases of unclassified posterior uveitis, and analyzed IL-6 levels from vitreous samples." (PMID 38232093, 2024). "Here we report changes in vitreous opacity in posterior uveitis as observed using WOCT imaging, IL-6 levels and their relationship." (PMID 38232093, 2024). "The relationship between vitreous IL-6 levels and image findings from WOCT from 37 eyes (34 patients) with posterior uveitis were analyzed." (PMID 38232093, 2024). "Further investigations into the relationship between vitreous IL-6 levels and clinical parameters including gender and CRP for the diagnosis and prognosis of posterior uveitis are needed." (PMID 36902507, 2023). "Considering this study, there may be a relationship between vitreous IL-6 concentration and serum CRP expression levels in posterior uveitis as well." (PMID 36902507, 2023).
postherpetic neuralgia (4 papers, 2020 to 2025). "The results of multi-factor Logistic regression analysis showed that age, CD4+/CD8+ ratio, Treg cell ratio, IL-6, TNF-α, and IL-10 were the independent risk factors for postherpetic neuralgia (p < 0.05)." (PMID 40606470, 2025). "IL-6 has been related to postherpetic neuralgia, neuropathic pain secondary to disc herniation, and the carpal tunnel syndrome." (PMID 32038662, 2020). "Among them, the erythrocyte sedimentation rate, CRP level, CGRP level, and interleukin-6 level of group B were significantly lower than those of group A. The incidence of postherpetic neuralgia (PHN) in group B patients (6.25%) was also lower than that in group A patients (25%)." (PMID 35450055, 2022).
pregnancy (4 papers, 2019 to 2025). The status during which female mammals carry their developing young (EMBRYOS or FETUSES) in utero before birth, beginning from FERTILIZATION to BIRTH. "We found significantly increased expressions of BAFF mRNA or protein in whole tissue samples, and serum levels of BAFF, TNF-α and IL-6 in whole blood samples from patients with salpingitis and tubal pregnancy, in comparison to the control group." (PMID 31088412, 2019).
proctitis (4 papers, 2015 to 2025). An inflammatory process affecting the anus. "The protective effect of 3-hydroxybutyrate (3-HB) in radiation-induced proctitis primarily occurs through inhibiting GPR43-mediated IL-6 signaling." (PMID 41450947, 2025). "A set of biomarkers (pro-hepcidin, IL-6, TNF, hemoglobin, ferritin, transferrin) and genetic polymorphisms were linked to proctitis." (PMID 40506902, 2025). "Supplementing with 3-HB (or restoring A. muciniphila) reinstates GPR43 inhibition, reduces STAT3 phosphorylation, and significantly lowers the inflammatory cytokine IL-6, thereby improving histological damage and clinical symptoms in radiation-induced proctitis." (PMID 41450947, 2025). "In this study, the incidence of PCa was higher in patients with pancolitis-type UC, suggesting that widespread inflammation, including that of IL-6, may be more involved in PCa development than in other types, such as proctitis or left-sided colitis." (PMID 38592255, 2024). "Additionally, with respect to the site of involvement in patients with UC, the IL-6 (P = 0.597), CRP (P = 0.076), and hepcidin (P = 0.968) levels were not significantly different between patients with proctitis, left-sided colitis, and extensive colitis." (PMID 25628652, 2015).
radicular cysts (4 papers, 2020 to 2023). "The objective of this study was to determine the association of oxidative stress and the production of inflammatory mediators MMP-9 and interleukin 6 (IL-6) in systemic events in radicular cyst growth." (PMID 32467797, 2020). "Further, IL-6 plays an important role in the pathogenesis of radicular cysts." (PMID 37400519, 2023).
radiodermatitis (4 papers, 2018 to 2025). A cutaneous inflammatory reaction occurring as a result of exposure to biologically effective levels of ionizing radiation. "The expression and protein level of IL-6 in plg+/+ mice began to increase from day 5 and reached the highest level from days 9 to 12 post irradiation when radiodermatitis developed." (PMID 30323258, 2018).
reactive arthritis (4 papers, 2014 to 2025). Reactive arthritis (ReA) is an autoimmune disorder belonging to the group of seronegative spondyloarthropathies and is characterized by the classic triad of arthritis, urethritis and conjunctivitis. "In a retrospective study with 34 patients with RA, 46 patients with reactive arthritis and 112 healthy subjects, the authors measured serum levels of IL-6, TNF and cortisol." (PMID 25608777, 2014). "The absolute levels of IL-6 were lower in healthy controls than in reactive arthritis and RA patients." (PMID 25608777, 2014). "This patient suffered from reactive arthritis, high CRP, and exceptionally high IL-6 levels around 400 ng/mL." (PMID 40687784, 2025).
retinopathy of prematurity (4 papers, 2020 to 2024). A bilateral retinopathy characterized by neovascularization, scarring, retinal detachment, and eventually blindness. "They found that a single 5 μg dose of IVT metformin reduced expression of several key SASP genes, such as Il6, Cdkn1a, and Cdkn2a, as well as decreased protein levels of IRE1α and NF-κB, highlighting the potential therapeutic effects of IVT metformin in retinopathy of prematurity." (PMID 39518910, 2024).
SAPHO syndrome (4 papers, 2015 to 2025). SAPHO syndrome (acronym for Synovitis, Acne, Pustulosis, Hyperostosis and Osteitis) is an auto-inflammatory disease, mainly characterized by the association of neutrophilic cutaneous involvement and chronic osteomyelitis. "In SAPHO syndrome, excessive IL-6 expression is strongly linked to the development of osteitis and skin lesions." (PMID 39286247, 2024). "The novelty of our work is that we assessed the association between IL-6, IL-23, and disease activity in patients with SAPHO syndrome." (PMID 26339141, 2015). "Previous studies have shown that proinflammatory cytokines—such as TNF-α, interleukin (IL)-1β, IL-6, and IL-8—are strongly expressed in patients with SAPHO syndrome, promoting an amplified inflammatory response." (PMID 41303152, 2025). "Interleukin-6 (IL-6) plays a pivotal role in SAPHO syndrome by promoting the proliferation and differentiation of B cells and T cells, thereby enhancing the immune response." (PMID 39286247, 2024). "In this study, we evaluated the relationship between serum levels of IL-6 and IL-23 and activity of AS, PsA, and SAPHO syndrome." (PMID 26339141, 2015). "There were no data in the available literature concerning serum levels of IL-6 and IL-23 in SAPHO syndrome." (PMID 26339141, 2015). "This article reviews the cytokines involved in the pathogenesis of SAPHO syndrome, such as tumor necrosis factor α (TNF-α), interleukin 1β (IL-1β), IL-6, IL-10, and transforming growth factor-β (TGF-β), and discusses their potential as intervention points for treatment." (PMID 39286247, 2024).
scrapie (4 papers, 2012 to 2024). A fatal disease of the nervous system in sheep and goats, characterized by pruritus, debility, and locomotor incoordination. "In fact, statistically significant differences were found in the expression of IL-1 (**p < 0.01) and IL-6 (*p < 0.05) between the healthy control sheep and the sheep in the terminal stage of scrapie." (PMID 39493812, 2024). "Several murine models of classical scrapie show that pro-inflammatory cytokines like IL-1, IL-6 and TNF-α, have increased expression at both mRNA and protein levels in brain, peripheral lymphoid tissue and serum at the terminal end stage." (PMID 22805457, 2012). "The analysis of cytokine levels revealed the overexpression of TGF-β, IL-10, and IL-6 in the thalamus of the scrapie-infected versus control sheep, but no alterations in the hippocampus." (PMID 35408945, 2022).
secondary hypogonadism (4 papers, 2013 to 2024). "In agreement with our finding is a previous report on 14 men of corresponding age with hypogonadotropic hypogonadism, in who increased levels of TNFa and IL6 was observed upon withdrawal of androgen replacement therapy." (PMID 23637840, 2013). "In T2D, secondary hypogonadism may result from both peripheral and central IR, aggravated by pro-inflammatory cytokines like Tumor Necrosis Factor Alpha (TNF-α) and Interleukin 6 (IL-6) that influence the HPG axis." (PMID 38892561, 2024).
sialadenitis (4 papers, 2016 to 2025). Sialadenitis is an infection of the salivary glands. "Both TNF-α and IL-6 have been implicated in inflammatory salivary gland diseases such as Sjogren's disease and irradiation-induced sialadenitis." (PMID 39813519, 2025). "Clinicopathologically, increased IL-6 levels were reported in IgG4-RD and IL-6 was elevated in IgG4-related dacryoadenitis and sialadenitis." (PMID 34246246, 2021). "The immunochemical analysis of the retroperitoneum tissue revealed higher IL-6 and IL-6R expression in both the tissue of IgG4-related RPF and IgG4-related sialadenitis than in the control tissue." (PMID 32733444, 2020). "Interestingly, we have found remarkably higher levels of IL-6 and IL-6R expression in both the IgG4-related RPF and IgG4-related sialadenitis tissues." (PMID 32733444, 2020).
skin abscess (4 papers, 2020 to 2023). "Our findings indicate that mleS is involved in enhancing skin abscess formation and that this process may be associated with increases in IL-6 and lactic acid production and the promotion of S. aureus survival within macrophages." (PMID 37052483, 2023). "The results obtained provided evidence to indicate that mleS is involved in enhancing mouse skin abscess formation accompanied by increases in the production of interkeukin-6 (IL-6) and lactic acid, as well as promoting survival within host macrophages." (PMID 37052483, 2023). "Compared with mice treated with NS, ERM, 8 mg/kg or 16 mg/kg of VAN, bacterial loads in the skin abscesses and IL‐6 levels in the sera were significantly lower in mice treated with 32 mg/kg of VAN at 11 days." (PMID 38818266, 2023). "Mouse skin abscess caused by the BS19-mleS mutant strain (isogenic mleS mutant in an ST59 isolate) was significantly attenuated and associated with reductions in interleukin-6 (IL-6) and lactic acid production." (PMID 37052483, 2023).
small vessel stroke (4 papers, 2021 to 2025). "Previous MR analyses have shown links between genetically proxied inhibition of IL‐6 and a lower risk of small vessel stroke." (PMID 41182006, 2025).
squamous cervical cancer (4 papers, 2015 to 2025). "By using a qRT-PCR array, we identified CD3E, IL6, VEGFA and a high IL6/IL17 ratio combined with low IL5 expression as the most prognostic factors in squamous cervical cancer." (PMID 25889974, 2015).
Stillbirth (4 papers, 2018 to 2025). Death of the fetus in utero after at least 22 weeks of gestation. "Interestingly, we found that low cord blood IL-6 level was associated with stillbirth or neonatal death." (PMID 30517142, 2018). "The levels of IL-6 (P = 0.02) and IL-1β (P = 0.01) were significantly higher in the serum of stillbirth sows than that in normal sows." (PMID 36741405, 2022). "As we expected, the serum levels of TLR4, IL-6 and IL-1β had higher concentration in the stillbirth sow group." (PMID 36741405, 2022). "We found that decreasing GA at birth and IL-6 were significant predictors or stillbirth or neonatal death." (PMID 30517142, 2018). "In stillbirth cases, elevated pro-inflammatory cytokines such as IL-6 and IFN-γ suggest immune dysregulation may precipitate pregnancy failure." (PMID 41002999, 2025).
streptococcal infection (4 papers, 2011 to 2024). Any of the several infectious disorders caused by members of streptococcus, a genus of gram positive bacteria belonging to the family Streptococcaceae. "Additionally, the patient's elevated IL‐6 levels and the initial treatment with penicillin for a suspected streptococcal infection raise the intriguing possibility of an infectious trigger in this case." (PMID 38827940, 2024). "Thus, the observed M1 protein-induced rise in IL-6 may not only be regarded as a sign of general activation of innate immunity but also as a pathophysiological link between streptococcal infection and a failing circulatory system." (PMID 30041663, 2018). "Although IL-6 is known to be critical for some Th17 responses in mice, it is not known whether this is the case for streptococcal infection." (PMID 21966268, 2011).
sweet syndrome (4 papers, 2007 to 2019). "We analyzed the circulating levels of interleukin-1β, interleukin-6, interleukin-18, neopterin, and soluble tumor necrosis factor receptors I and II, in order to clarify the pathogenesis of Sweet’s syndrome." (PMID 28668093, 2017). "In summary, granulocyte-colony stimulating factor, granulocyte macrophage colony stimulating factor, interferon-gamma, interleukin-1, interleukin-3, interleukin-6, and interleukin-8 are potential cytokine candidates in the pathogenesis of Sweet's syndrome." (PMID 17655751, 2007). "Cytokines, such as granulocyte colony stimulating factor (G-CSF), interleukin (IL)-1, IL-6, or IL-8, if deposited in the dermis, may be responsible for the immunopathologic and clinical manifestations of Sweet's syndrome." (PMID 18588703, 2008).
systemic mastocytosis (4 papers, 2022 to 2025). Systemic mastocytosis (SM) comprises a heterogeneous group of rare acquired and chronic hematological malignancies that are related to an abnormal proliferation of mast cells in tissue, including bone marrow, with or without skin involvement. "Indeed, additional germline variants in KIT and in genes encoding for cytokines or their receptors (e.g., IL13, IL6, IL6R, IL31, IL4R), as well as increased copy numbers of the TPSAB1 gene encoding for α‐tryptase, have been increasingly recognized as associated with systemic mastocytosis in adults." (PMID 41177946, 2025).
Tension-type headache (4 papers, 2016 to 2023). A type of headache that last hours with continuous pain of mild or moderate intensity, bilateral location, a pressing/tightening (non-pulsating) quality and that is not aggravated by routine physical activity such as walking or climbing stairs. "Tension type headache also have been associated with elevated levels of IL-6 or IL-8." (PMID 34088273, 2021). "After 6 months, serum IL-6 levels were gradually returned to normal in recovered patients, and the prevalence of tension-type headache was decreased from 38 to 2%." (PMID 35527821, 2022).
thoracic aortic aneurysm (4 papers, 2022 to 2025). An aneurysm formed in the wall of the proximal portion of the descending aorta proceeding from the arch of the aorta. "While levels of several inflammatory biomarkers such as C-reactive protein (CRP) and interleukin (IL)-6 are elevated in patients with thoracic aortic aneurysms, suggesting the effects of systemic inflammation on the pathophysiology." (PMID 35473483, 2022).
thyroid tumor (4 papers, 2019 to 2023). A benign or malignant neoplasm affecting the thyroid gland. "Moreover, HHV-6A strongly induced the release of IL-6, cytokine reported to promote cancer progression, including that of thyroid tumors." (PMID 37896899, 2023). "The cytokines IL-6 and IL-8 (CXCL-8) are further key elements which are able to enhance 3D growth in PC-3 and have both already shown to induce 3D growth in thyroid tumor cells grown under 1g-conditions using the liquid overlay technique." (PMID 35252204, 2022). "Additionally, based on the PCR result, several inflammatory factors, such as Survivin, CD44, NF-kappaB, and IL-6, were higher expressed in the EBV-positive groups, and the mRNA expression of EBER1 and EBER2 was higher in thyroid tumor group." (PMID 31134145, 2019).
tic disorder (4 papers, 2020 to 2024). Disorders characterized by recurrent TICS that may interfere with speech and other activities. "Apart from TNF-α (p = 0.159) and IL-6 (p = 0.198) among children with tics and IL-17 among controls (p = 0.129, Kolmogorov‒Smirnov test with Lilliefors correction), none of the cytokines conformed to assumptions of normality." (PMID 38956051, 2024). "Next, we sought to evaluate the correlation between upregulated cytokines (IL-1β, TNF-α, IL-6, and IL-4) in children with tic disorders." (PMID 38956051, 2024). "Serum IL-1β, TNF-α, IL-6, and IL-4 levels were higher in children with tic disorders than in healthy controls, which is in line with the qRT-PCR data." (PMID 38956051, 2024). "We found that children with tic disorders had significantly elevated levels of IL-1β, TNF-α, IL-6 and IL-4 expression, while we detected lower expression levels of IL-17 in children with tic disorders." (PMID 38956051, 2024). "Additionally, although not directly about tic disorders, some studies found that OCD patients, which is comorbid with tic disorder, have increased monocytes compared to healthy controls, which in turn release more cytokines including GM-CSF, IL-1β, IL-6, IL-8, and TNF-α." (PMID 37907857, 2023). "In our study, children with tic disorders had significantly elevated levels of IL-1β, TNF-α, IL-6 and IL-4 expression, while controls had significantly elevated levels of IL-17 expression." (PMID 38956051, 2024). "According to univariate ANOVAs, children with tic disorders had significantly elevated levels of IL-1β, TNF-α, IL-6 and IL-4 expression, while controls had significantly elevated levels of IL-17 expression." (PMID 38956051, 2024). "A recent meta-analysis summarizing 25 studies also identified small-to-large effect sizes for increased IL-6 levels and a large effect size for increased TNF-α levels in tic disorder patients." (PMID 37907857, 2023). "Finally, we compared children with tic disorders and control children in terms of cytokine expression (i.e., IL-1α, IL-1β, TNF-α, IL-6, TGF-β, IL-17, and IL-4) using qRT-PCR." (PMID 38956051, 2024).